PGA3 (pepsinogen A3)
Description:
Shows particularly broad specificity; although bonds involving phenylalanine and leucine are preferred, many others are also cleaved to some extent.
Tractability: Small molecule: it belongs to a druggable protein family. Antibody: UniProt places it where antibodies can reach, with medium confidence; UniProt predicts a signal peptide or a membrane-spanning region; its Gene Ontology location is reachable by antibodies, with medium confidence.
Gene: Protein-coding gene on chromosome 11 (61,203,307 to 61,213,098, forward strand). Ensembl gene ENSG00000229859.
Subcellular location: Secreted
Pathways (Reactome):
Metabolism of proteins: Surfactant metabolism
Gene Ontology:
Molecular function: aspartic-type endopeptidase activity
Biological process: proteolysis
Cellular component: extracellular exosome; multivesicular body lumen; extracellular region
Genetic constraint (gnomAD): Loss-of-function variants: 0 observed, 5.88 expected, observed/expected ratio (o/e) 0, 90% interval 0 to 0.51. That is too few expected variants to judge how well the gene tolerates losing a copy. Missense variants: 15 observed, 50.85 expected, observed/expected ratio (o/e) 0.29, 90% interval 0.2 to 0.45. Synonymous variants: 12 observed, 18.26 expected, observed/expected ratio (o/e) 0.66, 90% interval 0.42 to 1.07.
Homologues: Orthologues: macaque PGA4 (94% identical), pig PGA5 (82% identical), dog PGA (82% identical), tropical clawed frog pga4 (68% identical), Drosophila melanogaster Bace (43% identical), Drosophila melanogaster CG17134 (41% identical), Drosophila melanogaster CG6508 (39% identical), Drosophila melanogaster CG33128 (39% identical), Caenorhabditis elegans asp-1 (34% identical), Caenorhabditis elegans asp-16 (34% identical), Caenorhabditis elegans asp-17 (33% identical), Caenorhabditis elegans asp-18 (32% identical), and 6 more. Paralogues in human: PGA4 (99% identical), PGA5 (99% identical), CTSE (54% identical), PGC (50% identical), CTSD (45% identical), NAPSA (41% identical), REN (35% identical), BACE1 (30% identical), BACE2 (30% identical).
Diseases named in the same sentence as PGA3 in open-access papers:
PGA3 is named in the same sentence as 25 diseases in open-access papers, as found by Europe PMC text mining. Sharing a sentence is not in itself a finding about the gene and the disease. The quoted sentences say what the papers report.
gastric cancer (4 papers, 2015 to 2025). A primary or metastatic malignant neoplasm involving the stomach. "PGA3 is highly expressed in bone metastases of gastric cancer, indicating poor survival, and PGA5 expression can induce changes related to tumor progression and epithelial–mesenchymal transition." (PMID 41009814, 2025). "PGA3 and PGA5 are mainly expressed in ovarian cancer and lung cancer, while PGA4 is mainly expressed in lung cancer and gastric cancer cell lines." (PMID 33067881, 2020). "However, some genes such as HOXC9, FNDC1, STRA6, KCNE2, PGA3 and KCNJ16 haven’t been reported in gastric cancer and their roles remain unknown." (PMID 25928635, 2015).
gastric adenocarcinoma (3 papers, 2020 to 2025). "Conversely, the most significantly downregulated genes included LIPF (gastric lipase), PGA4 and PGA3 (pepsinogens), reflecting the characteristic loss of gastric digestive enzyme production in gastric adenocarcinoma." (PMID 40725485, 2025). "The expression of PGA3 and PGA4 increased in kidney renal clear cell carcinoma but decreased in thyroid carcinoma and stomach adenocarcinoma." (PMID 33067881, 2020).
prostate carcinoma (2 papers, 2018 to 2023). A carcinoma that arises from epithelial cells of the prostate gland. "Three proteins, β2 M (β2-microglobulin), PGA3 (pepsinogen 3), and MUC3 (mucin 3), were found to be significantly different between urine samples from BPH patients and samples from prostate cancer patients through univariate analysis." (PMID 30197761, 2018). "Furthermore, the urinary levels of β-2-microglobulin (β2M), pepsinogen A3 (PGA3), and mucin 3 (MUC3) were found to be elevated in prostate cancer patients." (PMID 38250812, 2023).
Barrett esophagus (1 paper, 2016). Esophageal lesion lined with columnar metaplastic epithelium which is flat or villiform. "PGA3, PGA4, and PGA5 encode pepsinogen A (PGA), and the differential expression of PGA3, PGA4, and PGA5 is related to the pre-neoplastic nature in patients with Barrett’s esophagus." (PMID 27855662, 2016).
bladder urothelial carcinoma (1 paper, 2020). "PGA3, PGA4, and PGA5 showed more copy number amplification in lung adenocarcinoma, esophageal carcinoma, kidney chromophobe, and copy number reduction in bladder urothelial carcinoma, lung squamous cell carcinoma, rectum adenocarcinoma, and cholangiocarcinoma." (PMID 33067881, 2020).
endometrial carcinoma (1 paper, 2020). A malignant tumor arising from the epithelium that lines the cavity of the uterine body. "It is worth noticed that all PGC, PGA3, and PGA5 genes had a certain degree of mutation in endometrial carcinoma, which is a tumor with high global mutation rate." (PMID 33067881, 2020).
lupus erythematosus (1 paper, 2025). An autoimmune, connective tissue chronic inflammatory disorder affecting the skin, joints, kidneys, lungs, heart, and the peripheral blood cells. "For instance, FAM71E1 and EMC10 have been associated with lupus erythematosus and genes like PGA3, VWCE, and PTOV1 are associated with immune infiltrates and immunity in various tumors." (PMID 41009814, 2025).
nephritis (1 paper, 2020). Inflammation of renal tissue. "The following potential proteases for the different CKD aetiologies were identified: ADPKD (MMP7), MCD (CTSB, CTSD, CTSE, MEP1A, MMP7, PGA3), MGN (MMP3, MMP7, MMP9, MMP13, MMP14), IgAN (MMP7), FSGS (MMP3, MMP7), vasculitis (PGA3), nephritis (MMP7, MMP9), nephrosclerosis (MMP7), and DKD (MMP9)." (PMID 32427855, 2020).
tumor (5 papers, 2020 to 2025). "The quantity and intensity of cellular interactions among PGA3+ tumor cells in cluster 0, MUC5AC+ tumor cells from cluster 1, TFF3+ tumor cells associated with cluster 2, and other diverse cell types were then illustrated." (PMID 40124374, 2025). "Among downregulated genes, the classic chief cell markers LIPF and PGA3 were among the top downregulated genes in tumor epithelial cells (P < 0.0001)." (PMID 34642171, 2022). "Notably, we found that PGA3+ tumor cells engage with other cell types through the MDK-NCL receptor-ligand pair." (PMID 40124374, 2025). "Both these genes were oncogenes, and downregulated genes such as ATP4A, ATP4B, PGA3, PGA4, and PGA5 were reported tumor suppressors in GC." (PMID 39283078, 2024).
cancer (4 papers, 2020 to 2024). A tumor composed of atypical neoplastic, often pleomorphic cells that invade other tissues. "The mutation rates of PGA3, PGA4, and PGA5 in all cancer lines were low and less than 2%." (PMID 33067881, 2020). "Using the count data of 33 human tumors covered by TCGA, we analyzed the differential expression of PG family genes including PGC, PGA3, PGA4, and PGA5 in different cancers at the overall level based on continuous variable analysis." (PMID 33067881, 2020). "PGA3, PGA4, and PGA5 are mainly involved in K‐RAS signaling pathway, bile acid metabolism, mitotic G2 M phase, and other cancer‐related pathways." (PMID 33067881, 2020). "PGA3, PGA4, and PGA5 were expressed in most normal tissues, but decreased in cancer tissues." (PMID 33067881, 2020). "The data of 21 kinds of cancers from The Protein Atlas showed that the expression of PGA3, PGA4, and PGA5 could not be detected in any cancer tissues." (PMID 33067881, 2020).
PGA3 also shares sentences with these, for which no sentence is quoted: atrophic gastritis (1 paper); autoimmune gastritis (1); cholangiocarcinoma (1); esophageal carcinoma (1); gastric diseases (1); HCMV infection (1); lung adenocarcinoma (1); lung carcinoma (1); lung squamous cell carcinoma (1); migraine (1); nephrosclerosis (1); ovarian carcinoma (1); rectum adenocarcinoma (1); thyroid carcinoma (1); vasculitis (1).